TMEM219 (transmembrane protein 219)
Description:
Cell death receptor specific for IGFBP3, may mediate caspase-8-dependent apoptosis upon ligand binding.
Synonyms: IGFBP-3R; IGFBP3R
Tractability: Antibody: UniProt places it where antibodies can reach, with high confidence; its Gene Ontology location is reachable by antibodies, with high confidence; UniProt predicts a signal peptide or a membrane-spanning region. PROTAC: ubiquitination databases record sites on it; its protein half-life has been measured.
Gene: Protein-coding gene on chromosome 16 (29,940,885 to 29,973,052, forward strand). Ensembl gene ENSG00000149932.
Subcellular location: Cell membrane
Gene Ontology:
Molecular function: protein binding
Biological process: apoptotic process; ERK1 and ERK2 cascade; negative regulation of inflammatory response; positive regulation of ERK1 and ERK2 cascade; regulation of transforming growth factor beta1 production; transforming growth factor beta1 production
Cellular component: receptor complex; plasma membrane
Genetic constraint (gnomAD): Loss-of-function variants: 20 observed, 20.39 expected, observed/expected ratio (o/e) 0.98, 90% interval 0.69 to 1.42. The upper end of that interval is the gene's LOEUF score, 1.42, which puts it in group 5 of 6, group 1 being the genes least tolerant of losing a copy. Missense variants: 288 observed, 306.51 expected, observed/expected ratio (o/e) 0.94, 90% interval 0.85 to 1.04. Synonymous variants: 113 observed, 129.9 expected, observed/expected ratio (o/e) 0.87, 90% interval 0.75 to 1.02.
Homologues: Orthologues: chimpanzee TMEM219 (99% identical), macaque TMEM219 (99% identical), guinea pig TMEM219 (89% identical), mouse Tmem219 (84% identical), rat Tmem219 (82% identical), pig TMEM219 (80% identical), zebrafish zgc:158398 (29% identical). Paralogues in human: TMEM248 (25% identical).